PHB1 (prohibitin 1)
Diseases named in the same sentence as PHB1 in open-access papers (continued):
Sharing a sentence is not in itself a finding about the gene and the disease.
hepatocellular carcinoma (10 papers, 2012 to 2025). A malignant tumor that arises from hepatocytes. "Meanwhile, liver-specific Phb1 knockout (KO) mice develop hepatocellular carcinoma (HCC) spontaneously by regulating MAX, MNT and MATα1." (PMID 36348375, 2022). "Hepatic DE genes in Phb1+/− mice showed increased risks of hyperplasia of the liver, apoptosis of liver cells, hepatic injury, and hepatoma and decreased functions in the proliferation of liver cells and fibrosis." (PMID 34539442, 2021). "Liver-specific Phb1 knockout mice showed a high ability to form spontaneous hepatocellular carcinoma." (PMID 30886235, 2019). "In addition, the treatment with the neddylation inhibitor MLN4924 in Phb1-KO mice, an animal model of hepatocellular carcinoma showing elevated neddylation, reverted the malignant phenotype." (PMID 25650664, 2015). "In human hepatocellular carcinoma (HCC) and cholangiocarcinoma (CCA) cells, PHB1 inhibits cell growth and negatively regulates the expression of oncogenes c-MYC, MAFG, and c-MAF." (PMID 30886235, 2019).
pancreatic cancer (10 papers, 2014 to 2021). "Forkhead protein 1 (FoxM1) has also been correlated with PTX resistance in human pancreatic cancer, through a pathway involving the overexpression of Prohibitin 1 (PHB1) and activation of the FoxM1/PHB1/RAF-MEK-ERK pathway." (PMID 33348838, 2020). "MDA-MB-231 and PANC1, models for breast and pancreatic cancer, respectively, were transfected with siRNA knocking down PHB1 and PHB2." (PMID 29643415, 2018). "In pancreatic cancer tissue, the expression level of PHB1 on plasma membrane was found to be higher than that in normal tissues, indicating an important role of PHB in tumorigenesis." (PMID 29784973, 2018). "Recently, rocaglamide was found to selectively bind to PHB1 and PHB2 with nanomolar affinity and to influence the membrane localization of PHB1 and PHB2 in the human T cell leukemic cell line Jurkat, the human cervical cancer cell line HeLa and the pancreatic cancer cell line AsPC-1." (PMID 26091791, 2015). "In MiaPaCa-2 pancreatic cancer cells, Akt phosphorylates PHB1 at Thr258 but does not phosphorylate PHB2." (PMID 26091791, 2015).
melanoma (9 papers, 2010 to 2024). A malignant, usually aggressive tumor composed of atypical, neoplastic melanocytes. "Interestingly, the PHB1 genotype C1703T in the 3′-UTR is correlated with an increase in the risk for melanoma in a high ultraviolet radiation region in Brazil114." (PMID 29784973, 2018). "Here, we demonstrate that miR-195, a classical tumor suppressor in many types of cancer, is down-regulated in melanoma and directly regulates PHB1 expression." (PMID 29126391, 2017). "Here, we investigate the role of miR-195, its impact on PHB1 expression, and on chemosensitivity in melanoma cells." (PMID 29126391, 2017). "This study support the role of miR-195 as anti-proliferative miRNA via targeting of PHB1 in melanoma cells." (PMID 29126391, 2017). "Our recent data shown that accumulation of PHB1 protects melanoma cells from chemotherapy-induced cell death." (PMID 29126391, 2017). "We observed PHB1 accumulation in the mitochondria and nucleus of melanoma cells after high doses of cisplatin and demonstrated that PHB1 knockdown sensitizes melanoma cells to cisplatin-induced cell death." (PMID 29126391, 2017). "We demonstrated that miR-195 regulates PHB1 directly by RT-qPCR and western blot in melanoma cells and luciferase assays." (PMID 29126391, 2017). "To corroborate the observed negative correlation, we analyzed the gene expression levels of PHB1 and miR-195 in 12 melanoma cell lines compared to melanocytes (NGM)." (PMID 29126391, 2017). "TCGA-RNAseq data obtained from 341 melanoma patient samples as well as a panel of melanoma cell lines were used in an expression correlation analysis between PHB1 and predicted miRNAs." (PMID 29126391, 2017). "Taken together, these data indicate that PHB1 up-regulation in melanoma could be due in part to a decrease in miR-195 expression." (PMID 29126391, 2017). "Indeed, recent results from our laboratory have shown that PHB1 accumulates in mitochondria after stress induced by cisplatin in melanoma cells." (PMID 29126391, 2017). "Moreover, RT-qPCR data showed that miR-195 is down-regulated while PHB1 is up-regulated in a collection of melanoma cells." (PMID 29126391, 2017). "To define regulators that could influence the expression of PHB1 in melanoma, we looked into the miRanda Database and identified 28 miRNAs with putative sites in the PHB1 3’UTR region." (PMID 29126391, 2017). "To establish PHB1 as a relevant target of miR-195, we conducted rescue experiments in which we showed that PHB1 transgenic expression could antagonize the suppressive effect miR-195 on the proliferation of melanoma cells." (PMID 29126391, 2017). "Furthermore, PHB1 accumulates in mitochondria of melanoma cells after anticancer treatment, leading to chemoresistance, and an elevated PHB1 level is reported in activated lymphocytes, characterized by resistance towards apoptosis, of patients affected by multiple sclerosis." (PMID 30669391, 2019). "Lacking of miR-195 expression in melanoma patients seems to be one of the main mechanisms of PHB1 accumulation in melanomas which could decrease the efficacy of chemotherapy and even target therapies like vemurafenib used in melanoma patients harboring BRAF V600E mutation." (PMID 29126391, 2017). "In parallel, we evaluated PHB1 and PHB2 protein expressions in three groups of seven melanoma lines each representing the three major molecular subtypes (WTBRAF/WTNRAS, MUTBRAF, and MUTNRAS)." (PMID 37508519, 2023). "miR-195 impact on PHB1 mRNA and protein levels and relevance of this regulation were investigated in UACC-62 and SK-MEL-5 melanoma lines by RT-qPCR and western blot, luciferase reporter and genetic rescue experiments." (PMID 29126391, 2017). "MicroRNA-195 is down-regulated in melanoma cells according to the TCGA database and shows a significant negative expression correlation with PHB1." (PMID 29126391, 2017).
melanoma (continued). "In the cytoplasm, PHB was detected mostly in the mitochondria of LB373 and Mel 85 melanoma cells, but in SKMel 37 cells there was no colocalization of PHB1 with mitochondria." (PMID 28562344, 2017). "PHB1 may serve as a novel druggable target in C-RAF-mediated vemurafenib resistance since treatment with the natural compound rocaglamide A disrupts the interaction between PHB1 and C-RAF in melanoma cells." (PMID 29126391, 2017).
Obesity (8 papers, 2013 to 2026). Accumulation of substantial excess body fat. "In addition, sexual dimorphism is associated with PHB1 regulation, obesity traits and immune response." (PMID 38813101, 2024). "For example, we have shown that transgenic mice overexpressing PHB1 in adipocytes develop obesity, which involves mitochondrial biogenesis, and others have reported that PHB1 has a role to play in mitochondrial phospho-lipid homeostasis in different model organisms." (PMID 35434552, 2022). "Thus, Mito-Ob and m-Mito-Ob mice have created unique opportunities to gain new insights into the role of obesity-related abnormalities in the adult-onset T1D and for defining the role of PHB1 in antigen presenting cells such as dendritic cells and macrophages." (PMID 29263933, 2017).
bladder cancer (7 papers, 2015 to 2025). "The overexpression of PHB1 was significantly associated with poor prognosis of bladder cancer patients." (PMID 37210546, 2023). "PHB1 is overexpressed in human bladder cancer tissues and mainly localized to mitochondria." (PMID 37210546, 2023).
glioma (6 papers, 2015 to 2025). A benign or malignant brain and spinal cord tumor that arises from glial cells (astrocytes, oligodendrocytes, ependymal cells). "Interestingly, it has been shown that GOLPH3 of human glioma U251 cells interacts with the cytosolic proteins PHB1 and PHB2, which have also been observed to be associated with mitochondria." (PMID 38391929, 2024). "Interestingly, miR-26a also binds directly to the 3′-UTR of PHB1, inhibiting its expression in glioma cells." (PMID 29784973, 2018). "In glioma cells, the oncomiR microRNA-26a promotes tumor growth and angiogenesis by targeting PHB1." (PMID 26091791, 2015). "However, in glioma cells, microRNA-27a promotes apoptosis by decreasing PHB1 protein expression." (PMID 26091791, 2015). "Several studies have reported that GOLPH3 promotes autophagy in glioma cells via PHB2 but not PHB1." (PMID 40168274, 2025).
lung carcinoma (6 papers, 2015 to 2025). "In paclitaxel-resistant lung cancer cells, PHB1 is mainly localized in the mitochondria and the plasma membrane, and knockdown of PHB1 activates the intrinsic apoptotic pathway following paclitaxel treatment both in vitro and in vivo." (PMID 26091791, 2015).
ovarian carcinoma (6 papers, 2008 to 2020). A malignant neoplasm originating from the surface ovarian epithelium. "Our previous study has shown that PHB1 down-regulation resulted in a transition of mitochondrial morphology from a normal reticular network to vesicular punctiform in ovarian cancer cells." (PMID 22479600, 2012). "Actually, punctiform mitochondria have been observed in our previous study upon PHB1-knockdown in ovarian cancer cells." (PMID 22479600, 2012). "Our previous work revealed that PHB1 is essential for stabilizing the mitochondrial integrity and membrane potential in human ovarian cancer cells and rat ovarian granulosa cells." (PMID 22479600, 2012). "The present study provides an overview on the role played by PHB1, TGF-β and LH in ovarian cancer." (PMID 28427435, 2017). "Results of the present work suggest that PHB1 expression, accompanied by decreased LH in serum, increased LHR mRNA expression in ovarian tissue and decreased TGF-B serum levels, may contribute to the proliferative activity of ovarian cancer cells." (PMID 28427435, 2017).
viral infection (6 papers, 2011 to 2026). "One of them is the prohibitin (PHB1), which is known for its role in cell-to-cell transmission of herpes virus and plays a pivotal role during other viral infections like that of Enterovirus and HCV." (PMID 35531299, 2022). "Here, we present the current understanding of PHB1 and PHB2 in bacterial and viral infection based on the cellular localization of PHBs at the plasma membrane, mitochondria, and cytoplasm." (PMID 42311502, 2026).
diabetes (5 papers, 2016 to 2024). "Our data from mice and primary retinal endothelial cell culture suggest that diabetes or high glucose conditions significantly increase prohibitin 1 protein levels." (PMID 35407523, 2022). "In that same paper, the authors reported that early diabetes led to decreased prohibitin 1 levels." (PMID 35407523, 2022). "Since prohibitin 1 is embryonically lethal when eliminated, future goals include the generation of endothelial cell-specific knockout mice to determine the actions of prohibitin 1 in the retinal vasculature, followed by the induction of diabetes." (PMID 35407523, 2022). "In addition, our data indicated that prohibitin 1 and 2 are upregulated in the kidney by diabetes and may have a potential role in early stages of diabetic nephropathy." (PMID 29121074, 2017).
esophageal squamous cell carcinoma (5 papers, 2012 to 2023). Esophageal squamous cell carcinoma (ESCC) is a type of esophageal carcinoma (EC) that can affect any part of the esophagus, but is usually located in the upper or middle third. "However, recent studies of PHB1 in esophageal squamous cell carcinoma (ESCC), gallbladder cancer, and bladder cancer exhibit promotion of cancer cell proliferation." (PMID 37190120, 2023).
leukemia (5 papers, 2012 to 2024). A malignant (clonal) hematologic disorder, involving hematopoietic stem cells and characterized by the presence of primitive or atypical myeloid or lymphoid cells in the bone marrow and the blood. "PHB1 is a direct target gene of WNT via the TCF4 site in the PHB1 promoter in leukemia cells." (PMID 38813101, 2024). "Additionally, the oncoprotein c-Myc, whose activation and deregulation by chromosomal translocations is a major feature of certain leukemias and lymphomas, was shown to target the PHB1 gene by binding and inducing its transcription on a specific consensus sequence." (PMID 29029444, 2017). "PHB1 and PHB2 levels in lymphoma and leukemia cells were compared to healthy peripheral blood mononuclear cells." (PMID 34868199, 2021). "Although prohibitins have been reported to localize to a variety of subcellular locations in tumor cells, PHB1 and PHB2 were shown to co-localize primarily to the mitochondria in Kit225 and leukemia/lymphoma patient tumor cells." (PMID 29029444, 2017). "Evidence is provided herein that PHB1 and PHB2 are overexpressed in a panel of leukemia and lymphoma cell lines compared to normal naïve PBMCs." (PMID 29029444, 2017). "Rather than protecting cells from apoptosis, PHB1 overexpression was found to encourage apoptosis of cells in leukemia with arsenic sulfide treatment." (PMID 34868199, 2021). "Moreover, PHB1 and PHB2 protein levels were significantly higher in tumor cells isolated from leukemia and lymphoma patients compared to healthy donor PBMCs and localized to primarily to the mitochondria." (PMID 29029444, 2017). "Indeed, PHB1 and PHB2 protein levels were significantly higher in tumor cells isolated from leukemia and lymphoma patients compared to PBMCs from healthy donors." (PMID 29029444, 2017). "Indeed, PHB1 and PHB2 protein levels were overexpressed in tumor cells isolated from patients with leukemia and lymphoma compared to normal naïve PBMCs." (PMID 29029444, 2017).
liver cancer (5 papers, 2015 to 2022). An epithelial or non-epithelial malignant neoplasm that arises from the liver. "Phb1 has also been shown to negatively regulate human and mouse liver cancer tumorigenesis through the downregulation of key oncogenes such as c-MYC." (PMID 35668443, 2022). "Collectively, these results may elucidate physiological changes by Phb1 and provide a comprehensive understanding of prognosis and prevention of liver injuries, containing liver cancer." (PMID 34539442, 2021). "To further study neddylation impact on liver cancer, we used Phb1-KO mouse model." (PMID 25650664, 2015). "Mice lacking Prohibitin 1 (Phb1), a mitochondrial chaperone protein, which regulates downstream signaling pathways, apoptosis, and transcriptional activation, in exhibit severe oxidative stress, fibrosis, and liver cancer." (PMID 32429417, 2020).
Sepsis (5 papers, 2020 to 2025). Sepsis is defined as life-threatening organ dysfunction caused by a dysregulated host response to infection. "The role and mechanism of PHB1 in sepsis will be further verified in gene knockout mice in our future work." (PMID 37359543, 2023). "We further revealed that the expression of PHB1 in these three clusters was significantly different and negatively correlated with the severity of sepsis, suggesting that PHB1 was involved in the development of sepsis." (PMID 37359543, 2023). "Our results showed that PHB1 was negatively correlated with the severity of sepsis patients, and the expression of PHB1 was also negatively correlated with the expression of NLRP3 inflammasomes." (PMID 37359543, 2023). "HDAC6 inhibits the mitochondrial protein PHB1, leading to increased oxidants and oxidative stress in sepsis." (PMID 35954428, 2022). "Taken together, these results indicated that HDAC6 expression has a significant inverse correlation with PHB1 levels, and that it directly correlates with disease severity in patients with sepsis." (PMID 32221047, 2020). "Herein, we found that PHB1 expression is significantly lower in PBMCs from sepsis patients than that in PBMCs derived from healthy controls." (PMID 32221047, 2020). "We also analyzed the correlations among HDAC6, PHB1, and mitochondrial dysfunction, and investigated their role in the development and progression of sepsis." (PMID 32221047, 2020). "To investigate the effects of HDAC6 and PHB1 on the development of sepsis, we measured the expression of HDAC6 and PHB1 in peripheral blood mononuclear cells (PBMCs) derived from sepsis patients and healthy controls." (PMID 32221047, 2020). "A negative linear correlation was observed between HDAC6 expression and that of PHB1 in PBMCs from sepsis patients (r2 = 0.6271, P = 0.0003)." (PMID 32221047, 2020). "We also observed that HDAC6 expression was higher while PHB1 expression was lower in the rats with CLP-induced sepsis compared to that in rats in the control group; this was consistent with the data obtained from human sepsis patients." (PMID 32221047, 2020). "Conversely, the expression of PHB1 mRNA and the production of PHB1 protein were dramatically lower in the rats with CLP-induced sepsis than that in the control rats (0.055 ± 0.021 vs 0.24 ± 0.032, P < 0.001)." (PMID 32221047, 2020). "Conversely, PHB1 mRNA expression was lower in PBMCs from sepsis patients as compared with PBMCs from healthy controls (0.05 ± 0.024 vs 0.62 ± 0.15, P < 0.001)." (PMID 32221047, 2020). "In conclusion, this study reveals that a high degree of mitophagy may predict a good outcome of sepsis, and PHB1 is a key NLRP3 inflammasome regulator via mitophagy in inflammatory diseases such as sepsis." (PMID 37359543, 2023). "In order to find the key regulatory factors related to mitophagy, through modular clustering analysis on sepsis samples, we further analyzed the obtained 22 key genes related to mitophagy, and further analysis revealed that PHB1 gene is one of the core genes of the overall network." (PMID 37359543, 2023). "Taken together, these results indicated that HDAC6 may promote the development of sepsis via regulation of PHB1-mediated mitochondrial function and homeostasis, in vivo." (PMID 32221047, 2020). "In the present study, we examined the effects of HDAC6 and PHB1 on the progression of sepsis." (PMID 32221047, 2020). "However, the related reports about the role of PHB1 in sepsis are still limited." (PMID 37359543, 2023). "Third, broad-spectrum antibiotic administration is considered to be the standard of care for patients with sepsis, but whether this treatment affects the expression of HDAC6 and PHB1 needs to be studied." (PMID 32221047, 2020). "To investigate the potential mechanism by which HDAC6 may promote sepsis development, we first determined the mitochondrial respiratory control rate, and then tested whether it correlated with the expression of HDAC6 and/or PHB1." (PMID 32221047, 2020).
Sepsis (continued). "Of note, when we analyzed the correlation between HDAC6 and PHB1 in PBMCs from sepsis patients, we found a negative linear correlation between the expression of HDAC6 and PHB1, meaning that the expression of PHB1 may be downregulated by HDAC6 during the development of sepsis." (PMID 32221047, 2020).
colitis (4 papers, 2021 to 2025). Inflammation of the colon. "Recent studies have also demonstrated that knocking out several genes encoding crucial mitochondrial proteins, such as voltage-dependent anion channel 1 (VDAC1) and prohibitin 1 (PHB1), can disrupt mitochondrial function and aggravate experimental colitis in mice." (PMID 40089459, 2025). "Prohibitin 1 is a chaperone for mitochondrial DNA, which expression is downregulated during active human IBD and DSS-induced colitis in mice, so its possible role in the pathogenesis of IBD may be mediated by excessive production of mtROS." (PMID 36359839, 2022).